SPP1 (secreted phosphoprotein 1)
Diseases named in the same sentence as SPP1 in open-access papers (continued):
Sharing a sentence is not in itself a finding about the gene and the disease.
pulmonary fibrosis (continued). "These TREM2+ macrophages may express SPP1 and are involved in liver and lung fibrosis, as well as fibrosis after myocardial infarction and atrial fibrillation." (PMID 40072075, 2025). "Therefore, SPP1, as a common molecular hub connecting immune cells, epithelial cells and ECM remodeling, plays a core role in the process of pulmonary fibrosis driven by different causes." (PMID 41293726, 2025). "SPP1 may influence lung fibrosis through its effects on anoikis and the PI3K/Akt signalling pathway." (PMID 39928535, 2025). "Single-cell analysis verified that monocyte-derived interstitial macrophages (Mo-IMs) exhibit a pro-fibrotic phenotype in the initial stages of pulmonary fibrosis and engage with fibroblasts via the SPP1 signaling pathway, facilitating EMT and ECM deposition, thereby advancing disease progression." (PMID 41293726, 2025). "Besides Spp1, the macrophage-specific deletion of Trem2, another gene differentially expressed by Gpnmb+Spp1+ macrophages, has been reported to reduce fibrosis in mouse models of pulmonary fibrosis and myocardial infarction." (PMID 40869418, 2025). "Spp1−/− mice are protected from developing silica-induced pulmonary fibrosis." (PMID 40559389, 2025). "Integrated multi-omics analyses of COVID-19-associated Rapid pulmonary fibrosis (RPF) patients and murine models reveal that CD163+ macrophages drive rapid pulmonary fibrosis progression via SPP1 secretion, identifying the CD163+-SPP1 axis as a potential therapeutic target." (PMID 41293726, 2025). "However, CD9+TREM2+CD63+ SAMs expressing Spp1 present in liver and lung fibrosis were presumed to have profibrotic role across species and tissues 24-26." (PMID 38505612, 2024). "Furthermore, studies have demonstrated that the downregulation of SPP1 effectively reduces pulmonary fibrosis in a bleomycin-induced pulmonary fibrosis mouse model." (PMID 38167532, 2024). "Among the top upregulated DEGs, notable markers included MMP7, a metalloproteinase involved in extracellular matrix (ECM) degradation and biomarker of pulmonary fibrosis; KRT17, an epithelial basal cell marker overexpressed in idiopathic pulmonary fibrosis; and SPP1, a biomarker of IPF." (PMID 38348044, 2024). "Secreted SPP1 has been reported to be significantly overexpressed in IPF, whereas SPP1-deficient mice models of pulmonary fibrosis exhibit reduced expression of COL1 and MMP2, as well as reduced pulmonary fibrosis." (PMID 39632841, 2024). "Notably, the transcription factor SPP1 has also been identified as a target for gene therapy of lung fibrosis." (PMID 39944354, 2024). "Macrophages with elevated SPP1 levels may thus play a pivotal role in IPF’s pulmonary fibrosis, particularly in the activation of myofibroblasts." (PMID 38566986, 2024). "A study on interstitial pulmonary fibrosis (IPF) indicates that Spp1 is predominantly expressed in myeloid cells within this condition, and IL-6 augments OPN expression in macrophages, which in turn sensitizes and directs fibroblasts toward other fibrogenic growth factors." (PMID 38001899, 2023). "Similarly, the expression levels of Vegfa and Spp1 were significantly increased in the pulmonary fibrosis mouse model." (PMID 37794454, 2023). "By searching the 18 candidate hub genes in GeneCards database, we found that CAV1 and PECAM1 were specifically expressed in lung tissues, BMP4 and VEGFA were related to angiogenesis, FYN and SPP1 were related to immunity or inflammation, and COL1A1 was closely associated with pulmonary fibrosis." (PMID 37794454, 2023). "In addition, macrophages can secrete SPP1 through exosomes, which promotes the transformation of fibroblasts into myofibroblasts and promotes pulmonary fibrosis." (PMID 37491214, 2023).
pulmonary fibrosis (continued). "Among those genes, we found that CAV1 and PECAM1 were specifically expressed in lung tissues, BMP4 and VEGFA were related to angiogenesis, FYN and SPP1 were related to immunity or inflammation, and COL1A1 was closely associated with pulmonary fibrosis according to the GeneCards database." (PMID 37794454, 2023). "There is considerable interest in OPN as a potentially useful pulmonary biomarker, especially in idiopathic pulmonary fibrosis and other idiopathic interstitial pneumonias which exhibit marked expansion of SPP1 positive alveolar macrophages compared to controls." (PMID 36864068, 2023). "Blocking SPP1 expression in mice inhibits the development of pulmonary fibrosis." (PMID 36685840, 2022). "Targeted SPP1 therapy might reverse the development of pulmonary fibrosis and prevent or delay the progression of pulmonary hypertension." (PMID 33816621, 2021). "Furthermore, small interfering RNA (siRNA)-mediated Spp1 knockdown mitigated lung fibrosis in a pulmonary fibrosis model." (PMID 34687701, 2021). "Secreted phosphoprotein 1 (SPP1, also known as osteopontin) increases in pulmonary fibrosis, and Spp1 transcription may be regulated by estrogen or estrogen receptor–related receptors." (PMID 26955063, 2016). "We determined whether differences in silica-induced SPP1 levels contribute to sex differences in lung fibrosis." (PMID 26955063, 2016). "For example, TGFB1 is an essential mediator of pulmonary fibrosis and can induce SPP1 expression." (PMID 26955063, 2016). "In addition, asbestos exposure in a murine lung fibrosis model results in up-regulation of SPP1 in bronchiolar epithelial cells." (PMID 25248511, 2014). "Furthermore, SPP1 is an anoikis gene in idiopathic pulmonary fibrosis." (PMID 38785271, 2024). "Moreover, SPP1 has been shown to have both pro-inflammatory and pro-fibrotic properties, and the SPP1 gene-expression level was found to increase in mouse models of pulmonary fibrosis and patients with IPF." (PMID 37794454, 2023). "Numerous studies indicate that SPP1-mediated ECM remodeling and EMT mechanisms are the primary determinants in the onset of several chronic lung diseases, including pulmonary fibrosis, silicosis, sarcoidosis, and chronic airway diseases." (PMID 41293726, 2025). "CD9+TREM2+ macrophages expressing GPNMB, SPP1, FABP5, and CD63 were reported in murine and human pulmonary fibrosis, enriched at the edges of scars." (PMID 37756565, 2023). "We identified three genes of interest (SPP1, COL1A1, and VEGFA) by bioinformatics analysis that were verified by qPCR in samples of TGF-β1-induced HFL fibroblast cells and pulmonary fibrosis mice." (PMID 37794454, 2023). "SPP1, THBS2, ITGB8, and some other genes screened out in this study have rarely been studied in the pathogenesis of pulmonary fibrosis, which also suggests possible approaches for subsequent pathogenesis studies." (PMID 33672678, 2021). "One of the most comprehensive resources for lung cell data is the Human Lung Cell Atlas, which has identified a population of SPP1+ macrophages co‐expressing LPL and CHIT1 across various disease conditions, including COVID‐19 and idiopathic pulmonary fibrosis (IPF)." (PMID 40395129, 2025). "Additionally, SPP1 increased the ratio of IL-17-producing T cells to IFN-γ-producing T cells, resulting in lung fibrosis." (PMID 38919629, 2024). "Moreover, a previous study confirmed the predicted emergence of CHI3L1- and SPP1- positive alveolar macrophages and increased CHI3L1 expression in AT2 cells in patients with pulmonary fibrosis." (PMID 35737303, 2022). "We hypothesize that the interaction between these cells, which express a myofibroblast-like gene module, and SPP1+ macrophages may play an important role in human TB granuloma development and PTLD, potentially aggravating granuloma progression and lung fibrosis." (PMID 41489684, 2026).
pulmonary fibrosis (continued). "Tuj1-expressing pericytes localize near SPP1+/arginase+ macrophages and express high levels of CXCL10, a chemokine that suppresses the pro-fibrotic macrophage differentiation, suggesting that this pericyte population contributes to counteracting the progression of pulmonary fibrosis." (PMID 41472685, 2025). "Notably, a comparable SPP1+ macrophage subset was observed in bronchoalveolar lavage fluid (BALF) samples from COVID‐19 patients, co‐expressing CD163, SPP1, and LGMN, and correlating with pulmonary fibrosis." (PMID 40395129, 2025). "Interestingly, SPP1 regulates macrophage polarization toward the anti-inflammatory M2 phenotype via upregulation of the Janus kinase 2 (JAK2)/STAT3 signaling pathway, resulting in pulmonary fibrosis." (PMID 38919629, 2024). "After secreted phosphoprotein 1 (SPP1) transfer, a marker of pulmonary fibrosis, to fibroblasts via M-sEVs, it activates the downstream cascade and leads to myofibroblast transition (FMT), promoting disease development, but the downstream reaction of SPP1 needs to be further studied." (PMID 35832790, 2022). "A pro-fibrotic macrophage phenotype (CD163/LGMN-Mp), expressing high levels of SPP1, recently identified in severe COVID-19 ARDS and IPF (idiopathic pulmonary fibrosis), was absent from CART-BAL, sarcoidosis and HC BALs." (PMID 36720972, 2023).
Obesity (104 papers, 2009 to 2026). Accumulation of substantial excess body fat. "While SPP1 has been implicated in general obesity, its markedly higher expression in postmenopausal women and pro-inflammatory effects in zebrafish suggest estrogen loss amplifies its pathogenicity." (PMID 40725440, 2025). "In obesity-driven chronic inflammation, SPP1 deficiency increases Tregs proportions, indicating that SPP1 overexpression normally suppresses Tregs accumulation." (PMID 41394841, 2025). "Osteopontin (OPN) is a widely expressed secreted glycosylated phosphoprotein encoded by the SPP1 gene that is involved in various pathophysiological processes including obesity, diabetes, and PCa." (PMID 35406450, 2022). "A hallmark of adipose tissue remodeling in obesity is induction of matricellular proteins, such as thrombospondins and osteopontin (SPP1), which regulate inflammatory, reparative, fibrogenic, and angiogenic responses." (PMID 34462518, 2021). "Mice fed on a high fat diet, or with genetic predisposition to obesity, show enormous elevation of SPP1 expression levels, while blocking SPP1 function by antibodies or genetic mutation improves insulin sensitivity." (PMID 33076817, 2020). "Increased expression levels of SPP1 are implicated in pathophysiological states associated with obesity and macrophage recruitment, as reviewed elsewhere." (PMID 28106759, 2017). "This study provides mechanistic insight into how metabolic dysregulation in obesity drives tumor progression through the SPP1-ECM axis." (PMID 41293726, 2025). "Recent studies also suggest that obesity can be prevented and reversed by inhibiting the aromatics receptor to reduce the liver expression of the SPP1 target gene." (PMID 40725440, 2025). "In summary, this study employed bioinformatics analysis of microarray and scRNA-seq datasets to identify three immune hub genes—SPP1, ITK, and CCL5—associated with obesity." (PMID 40725440, 2025). "SPP1 is an inflammatory cytokine highly upregulated in obese adipose tissue and it has been repeatedly shown to functionally promote obesity and regulate lipid synthesis." (PMID 39545257, 2024). "Under normal conditions, these cells exhibit minimal SPP1 expression but upregulate it in response to obesity." (PMID 38956667, 2024). "An upregulation of TLR4 (P < 0.05), CD68 (P < 0.05), SPP1 (P < 0.05) and CCL2 (P < 0.05) together with a downregulation (P < 0.05) of ADIPOQ levels in the jejunum from patients with obesity-associated T2D were found." (PMID 38315242, 2024). "Although SPP1 promotes obesity and regulates lipid synthesis, both of which drive fat deposition in hepatocytes." (PMID 36300106, 2022). "Specifically, the secreted SPP1 and the nuclear PPARγ and FTO were included among the down modulated genes associated to severe obesity pathway after PBMCs treatment with EVOO, while ADIPOQ was up regulated." (PMID 36386923, 2022). "SPP1 is upregulated in obesity and several models of liver injury.Studies have demonstrated a pivotal role of SPP1 in obesity-driven nutrition-dependent diseases, including NAFLD, suggesting SPP1 as a treatment target." (PMID 36300106, 2022). "Osteopontin, the protein codified by the SPP1 gene, is an inflammatory factor upregulated in obesity with a critical role in chronic inflammatory diseases and cancer." (PMID 34445187, 2021). "The identification of SPP1, ITK, and CCL5 as immune hub genes in the adipose tissue of postmenopausal obese women provides new insights into the immune dysregulation associated with obesity." (PMID 40725440, 2025). "A possible link between SPP1/OPN and obesity has been reported as CD153+PD-1+CD4+ T cells cause inflammation of visceral adipose tissue and insulin resistance under HFD conditions or in obesity by secreting SPP1/OPN." (PMID 37670786, 2023).
Obesity (continued). "In obesity, Timp1 (tissue inhibitor of metalloproteinases 1), Spp1 (osteopontin/secreted phosphoprotein 1), PAI-1 (plasminogen activator inhibitor-1) and Igfbp3 (insulin-like growth factor-binding protein 3) significantly increase in adipose tissue and contribute to the insulin resistance." (PMID 31576964, 2020). "Similarly, the upregulation of SPP1 underpins an increased infiltration of immune cells and the resulting inflammatory process, as this gene is highly induced during inflammation in obesity." (PMID 26798656, 2016). "In IR, obesity, metabolic syndrome, and NAFLD-related HCC, PI3K-AKT-PTEN, osteopontin (SPP1), and CXCL 10 expression are frequently amplified." (PMID 37726886, 2023). "OPN (secreted phosphoprotein 1, SPP1), a matricellular protein that acts as a cytokine, is highly upregulated in adipose tissue in obesity." (PMID 30951532, 2019). "Macrophage‐derived SPP1 is a pleiotropic AF catalyst in HOMER mice (i.e. combining hypertension, obesity and mitral valve regurgitation) so that bone marrow transplantation from Spp1−/− to HOMER mice prevents left atrial enlargement (LAE), LV hypertrophy and ultimately AF inducibility and burden." (PMID 41562403, 2026). "The results indicated a significant increase in the expression of SPP1 and TNF-α due to obesity." (PMID 38956667, 2024). "Collectively, these findings further support that obesity was accompanied by NAFLD and TH resistance and that SPP1 and TRβ may be involved in this pathological process." (PMID 36300106, 2022). "Additionally, a direct correlation between BMI and gene expression was observed for AGER, ANGPT2, CD68, IFI30, NOTCH3 and SPP1, whereas an inverse correlation was achieved for DLL4, PLIN, PNPLA2 and VEGF (genes that were down-regulated due to obesity)." (PMID 33022994, 2020). "Besides expressing SPP1, we found that SPP1+ TAM also expressed APOC4-APOC2, a gene not reported by previous RCC studies, and TREM2, which has been reported in various biological and pathological processes such as obesity and cancer." (PMID 36423636, 2022).
liver fibrosis (93 papers, 2008 to 2025). "Conversely, the deletion of Spp1 (encoding OPN) has been shown to alleviate liver fibrosis in multiple murine models." (PMID 40678531, 2025). "The causal relationship among hepatic glycogen storage, liver fibrosis progression, and SPP1 modulation requires further investigation." (PMID 38557493, 2024). "All these data indicate that induction of Spp1 gene expression by hepatocyte CEBPA deficiency predominantly contributes to the enhanced MASH-associated liver fibrosis." (PMID 38557493, 2024). "In this study, we focus on SPP1+ macrophages and extend their known association with lung and liver fibrosis to other tissues such as the endometrium." (PMID 37706477, 2023). "SPP1 encodes the chemokine osteopontin and has been linked to hepatic fibrosis via activation of HSC26 but was recently also shown as marker for recruited lipid-associated macrophages, underlining the important role of the heterogenous population of myeloid cells in fibrosis progression." (PMID 39996122, 2025). "Thus, hepatic SPP1 expression strongly tracks with liver fibrosis both in human and in hepatocyte CEBPA-deficient mice during MASH progression." (PMID 38557493, 2024). "Although the precise mechanism underlying the role of Spp1 in fibrosis remains unknown, Spp1 is a pivotal cytokine/chemokine generated by the Kupffer cells in response to liver damage that induces inflammation, which is a contributing factor in liver fibrosis." (PMID 22281153, 2012). "Future studies evaluating the therapeutic potential of the dual inhibition of FGF18 and OPN—both in liver fibrosis and in cancers with elevated Fgf18 and Spp1 expression—are warranted." (PMID 40678531, 2025). "During the course of NASH, stressed and dead liver parenchymal cells release profibrotic factors such as SPP1, which further recruit and activate liver macrophages and hepatic stellate cells, thereby exacerbating the process of liver fibrosis." (PMID 40124784, 2025). "Herein, by using biopsies from human livers, a strong positive correlation of hepatic SPP1 mRNA with liver fibrosis markers was further found." (PMID 38557493, 2024). "A subset of macrophages expressing SPP1, GPNMB, FABP5, and CD63 have also recently been identified in pulmonary and hepatic fibrosis associated with scar formation." (PMID 38902328, 2024). "Our study also revealed that schistosome infection leads to activation of and an increase in collagen signaling pathways, as well as the SPP1 signaling pathway, in liver fibrosis via scRNA-seq." (PMID 39590301, 2024). "Liver OPN protein was increased by MASH in human livers, and liver SPP1 mRNA positively correlated with liver fibrosis markers." (PMID 38557493, 2024). "The Spp1 enhancer was found to be hypo-methylated and its expression increased in early-stage liver fibrosis." (PMID 36594057, 2023). "Macrophage, populated in the liver during NAFLD, express a high level of Spp1, Cd9, and Trem2 and participate in hepatic fibrosis." (PMID 37822923, 2023). "Mechanistically, FN1 expressed from iECs led to the upregulation of Itgα5/β1 and Hnf4α in iHEAs and were correlated to the decreased expression of genes related to hepatic stellate cell activation such as Lox and Spp1 in the cholestatic liver fibrosis animals." (PMID 35883684, 2022). "Studies have reported that SPP1 participates in inflammation, liver fibrosis, and HCC, therefore taking center roles in chronic liver diseases." (PMID 36676937, 2022). "Two bioinformatics tools, IPA and Oncomine, indicated that Spp1 is related to liver fibrosis and inflammation." (PMID 22281153, 2012). "Detailed analyses revealed that in early-stage liver fibrosis, the Spp1 enhancer was hypomethylated and Spp1 expression was up-regulated." (PMID 22281153, 2012). "Spp1, encoding osteopontin (OPN), is a potent inducer of liver fibrosis." (PMID 39840059, 2024). "Hepatocyte CEBPA/SPP1 axis modulates CCl4-induced liver fibrosis." (PMID 38557493, 2024).